HNRNPCL4 (heterogeneous nuclear ribonucleoprotein C like 4)
Tractability: PROTAC: ubiquitination databases record sites on it.
Gene: Protein-coding gene on chromosome 1 (13,163,914 to 13,165,631, reverse strand). Ensembl gene ENSG00000179412.
Subcellular location: Nucleus
Subcellular location (Human Protein Atlas): Nucleoplasm
Gene Ontology:
Molecular function: RNA binding; nucleic acid binding
Cellular component: nucleus
Homologues: Orthologues: rabbit HNRNPC (88% identical), mouse Hnrnpc (87% identical), rat LOC100911576 (87% identical), tropical clawed frog hnrnpc (73% identical). Paralogues in human: HNRNPCL3 (100% identical), HNRNPCL1 (94% identical), HNRNPCL2 (92% identical), HNRNPC (88% identical), RALYL (44% identical), RALY (43% identical).
Diseases named in the same sentence as HNRNPCL4 in open-access papers:
HNRNPCL4 is named in the same sentence as 1 disease in open-access papers, as found by Europe PMC text mining. Sharing a sentence is not in itself a finding about the gene and the disease. The quoted sentences say what the papers report.
infectious disease (1 paper, 2023). A disorder directly resulting from the presence and activity of a microbial, viral, or parasitic agent in humans. "TSPY4, OPN1LW, CARF, CCDC14, HNRNPCL4, SSX2B genes need further exploration as it has not been identified in any infectious disease, including the recent COVID-19 pandemic." (PMID 37644081, 2023).